EGFR (epidermal growth factor receptor)
Diseases named in the same sentence as EGFR in open-access papers (continued):
Sharing a sentence is not in itself a finding about the gene and the disease.
cancer (continued). "One of the main issues of EGFR-based therapies in cancer cells is constitutive activation of EGFR-mediated downstream oncogenic signaling (MAPK, PI3K/AKT, JAK/STAT, and AKT/NF-kB pathway) by EGFR mutation, which thereby leads to the development of treatment resistance." (PMID 33244087, 2020). "It therefore appears that DHX9 may contribute to the overexpression of cyclin D1 in cancer following oncogenic EGFR upregulation, thus promoting proliferation and replicative immortality." (PMID 33437516, 2020). "Moreover, the biological connection inferred by the Ingenuity Pathway Analysis indicated these highlighted genes are closely connected to EGFR, which plays a significant role in cancer cell proliferation, providing evidence for our comprehensive analyses." (PMID 33424926, 2020). "As a result, EGFR has become one of the most popular cancer treatment targets." (PMID 32793499, 2020). "Both HBXIP and EGFR were reported as targets of miR-520b in other cancer cells." (PMID 32214367, 2020). "The A431 cell line is as a well-known model for EGFR-overexpressing cancer." (PMID 33003324, 2020). "A synergistic antibody combination containing two antibodies which bind to different epitopes of EGFR, called as Sym004, induced rapid internalization and degradation of EGFR that leads to down-regulation of EGFR and subsequent inhibition of cancer cell growth." (PMID 32079107, 2020). "Overexpression of EGFR can happen at early stage carcinogenesis of the head and neck, and can rise progressively together with other histological abnormalities, from hyperplasia to dysplasia, in situ carcinoma, and invasive carcinoma." (PMID 33324546, 2020). "In addition, DIM inhibited cancer cell invasion by suppression of metastasis-associated protein 2 (MTA2), NF-κB, interleukin 1 receptor-associated kinase 1 (IRAK1), and epidermal growth factor receptor (EGFR) based on upregulation of miR-146a." (PMID 35582221, 2020). "At the tissue level, administration of a certain amount of local anaesthetics topical or local has shown to have a direct inhibitory effect on the action of epidermal growth factor receptor (EGFR) which is a potential target for anti-proliferation in cancer cells." (PMID 32807213, 2020). "EGFR is overepressed in many cancer types and activated by a variate of ligands, including besides EGF also the transforming growth factor-alpha (TGFA), heparin-binding EGF-like growth factor (HBEGF), betacellulin (BTC), amphiregulin (AREG) and epiregulin (EREG) and epigen (EPGN)." (PMID 32119655, 2020). "Finally, we demonstrated here that KIAA1199 promotes NSCLC oncogenesis through EGFR signaling, which agreed with previous findings in other cancer types." (PMID 32519472, 2020). "At the same time, EV proteins were involved in the “negative regulation of epidermal growth factor receptor signaling”, “Rap1 signaling pathway”, “microRNAs in cancer”, “integrin cell surface interactions”, “ECM-receptor interaction”, and “platelet activation, signaling, and aggregation” groups." (PMID 32916986, 2020). "It is well known that EGF receptors (EGFR) are concentrated on many cancer cells." (PMID 32498278, 2020). "In this paper, we address the role of EGFR in the functional cell properties, such as adhesion on collagen type I, invasion capacity and metastatic potential, as well as the expression of key matrix macromolecules related with cancer progression." (PMID 33050027, 2020). "It has been reported that the anti-cancer activities of cordycepin can be mediated by several putative receptors, such as adenosine receptors (ARs), death receptors (DRs), and the epidermal growth factor receptor (EGFR)." (PMID 33172093, 2020). "However, it is prudent to point out that targets such as GRP78, integrins, or EGFR are the subject of developing and/or developed therapeutic strategies against cancer." (PMID 32487760, 2020).
cancer (continued). "EGFR, which is overexpressed in varieties of cancers, is involved in several processes of tumor growth and progression and has already been utilized as a target for cancer treatment." (PMID 32974385, 2020). "The use of bispecific proteins targeting the EGFR/ADAM17 axis could be an innovative strategy for the treatment of EGFR-dependent cancers." (PMID 32050662, 2020). "Apart from EGFR, its downstream effectors are also commonly dysregulated in cancer." (PMID 32620824, 2020). "Inhibiting autophagy-mediated TKI-resistance may be considered as therapeutic strategy to overcome resistance TKIs in EGFR deregulated cancers." (PMID 32878084, 2020). "EGFR has emerged as an important therapeutic target for cancer treatment." (PMID 32190291, 2020). "In addition, Annexin A2 has a known clinical association with cancer and has a role downstream of growth factor signaling pathways such as the IGF-IR and the EGFR pathways." (PMID 32629869, 2020). "Overall, the current evidence suggests that blocking the nuclear functions of EGFR may maximize the efficacy of EGFR-targeting agents and other anti-cancer therapies." (PMID 32321917, 2020). "c-Src and activated EGFR cooperate to induce cell transformation and cancer development." (PMID 32517369, 2020). "Indeed, we recently provide evidence that RCP stabilizes β1 integrin from lysosomal degradation and activation of the EGFR downstream signaling cascade, culminating in aggravation of cancer invasion and metastasis." (PMID 32728068, 2020). "In this regard, the facility that several genetic variations in the EGFR gene are a controversial hypothesis may apply to engage EGFR-targeted therapies to cancer patients." (PMID 33680380, 2020). "The epidermal growth factor receptor (EGFR) is considered as a potential target in cancer therapy." (PMID 32992587, 2020). "These anti-cancer effects may potentially result from inhibition of EGFR and downregulation of the PI3K/AKT/mTOR, NF-κB, and STAT3 signaling pathways." (PMID 32328465, 2020). "The EDVs are targeted to EGFR-expressing cancer cells by the anti-EGFR bispecific antibody." (PMID 32349317, 2020). "Thus, EGFR serves as a prognostic indicator in many types of cancer as its high expression is related to poor prognosis." (PMID 32337844, 2020). "Indeed, the authors added on their vesicles a peptide targeting EGFR on cancer cells that increased the specific delivery to cancer tissues after intravenous injection of exosomes in mice." (PMID 33271894, 2020). "This aptamer could become a safe and effective drug as it exhibits exquisite specificity toward EGFR-expressing cancer cells as reported by our group and others." (PMID 32024070, 2020). "The therapeutic effect of EGFR inhibition in cancers like HNSCC is mostly short-lived." (PMID 32054454, 2020). "Therefore, EGFR is one of the most important candidates for targeted cancer therapy and diagnosis by ligand-targeted NPs." (PMID 33003324, 2020). "We have reported that HIV+ exosomes induce the phosphorylation of ERK1/2 in an EGFR-dependent manner without causing canonical phosphorylation of the receptor in cancer cells." (PMID 32051269, 2020). "It has been reported that AQP8 in cancer cells is involved in cell migration via the EGFR pathway." (PMID 32260143, 2020). "High miR-34 is associated with multiple M1b metastatic type (P=0.020), cancer cell type (adenocarcinoma, P=0.009) and adenocarcinoma epidermal growth factor receptor (EGFR) mutation (negative, P=0.031)." (PMID 32283582, 2020). "PD-L1 constitutive expression in cancer cells may be due to several oncogenic pathways, including chromosome 9 amplification, PTEN deletions, PI3K/AKT, and EGFR mutations, MYC overexpression, CDK5 disruption, and increased PD-L1 transcription." (PMID 32824016, 2020). "The activated EGFR directly stimulates the cancer cell to proliferate." (PMID 32466280, 2020).
cancer (continued). "The found phylostratic effect of ploidy-associated c-MYC collaborating with bivalent genes, e.g., both H-RAS (stratum 1) and EGFR (stratum 6) may explain its critical role in cancer initiation when overexpressed, and cancer regression when locked." (PMID 33228223, 2020). "Although this case had the EGFR‐activating mutation, the maximum effect of afatinib was stable disease, lasting as short as three months, so some biological mechanisms other than the EGFR pathway may have contributed to the cancer progression." (PMID 32372482, 2020). "Indeed, several targeted nanoparticle formulations are now being tested in clinical trials for cancer treatment, decorated in their surface with antibodies against transferrin receptor, epidermal growth factor receptor, and ephrin type A receptor 2131." (PMID 32848154, 2020). "In particular, the pathway of pathways in cancer was enriched by 8 DEGs, such as EGFR and JUP." (PMID 33178610, 2020). "The EGFR-targeting cancer therapies are commonly facing drug resistance, mostly due to mutations." (PMID 32745124, 2020). "In summary, our findings suggest that enhanced TGF-β signaling via I227T/N236D mutation of TβRII promotes EGFR activation, leading to tumorigenesis of OSCC by enhancing the hallmark features of cancer, such as apoptotic resistance and more invasive phenotypic changes." (PMID 33246423, 2020). "Direct contact between cancer cells and CAFs is necessary for acquired resistance to EGFR-TKIs." (PMID 32546182, 2020). "Several EGFR‐specific mAbs and small‐molecule TKIs have been used in cancer therapy." (PMID 32592435, 2020). "This is consistent with the known role of EGFR in modulating the stroma to support cancer growth." (PMID 32696951, 2020). "Activated EGFR or HER2 predicts poor clinical outcome of cancer patients." (PMID 32398965, 2020). "In addition, aurisin A inhibits migration of cancer cells in a dose-dependent manner (p<0.001) and decreases the expression of epidermal growth factor receptor (EGFR) (p<0.05) and phosphorylated p38 (pp38) (p<0.05)." (PMID 31983163, 2020). "EGFR plays an important role in controlling the proliferation of cancer cells and also metastasis." (PMID 32765634, 2020). "However, chemo-resistant cancer cells usually exhibit increased autophagy induction despite showing EGFR overexpression." (PMID 31896739, 2020). "Amongst its cancer-related molecular interactions, Gal-3 has been shown to be a ligand for the RTKs epidermal growth factor receptor (EGFR) and vascular endothelial growth factor receptor-2 (VEGFR-2), activating signalling pathways for cell proliferation and angiogenesis respectively." (PMID 32664510, 2020). "EGFR is an essential receptor tyrosine kinase that can regulate cell proliferation and differentiation, and its abnormal activation contributes to a variety of human cancers." (PMID 33276757, 2020). "As EGFR can regulate cancer stem cells through both intracellular signaling and extracellular niches, SGCE may exert its roles in multiple ways." (PMID 32714745, 2020). "Nowadays, EGFR is known as an effective growth factor in many human cancers." (PMID 33374329, 2020). "Hence, NPs that have been designed to incorporate modified ligands that bind to EGFR in order to target EGFR-overexpressed cancer cells is a promising method of drug delivery." (PMID 32974385, 2020). "Evaluation of high serum cholesterol as a predictive biomarker of response to anti EGFR therapies in non recto-sigmoid cancers in retrospective/prospective studies may warrant further evaluation." (PMID 32594310, 2020). "The development of cancer drugs targeting the EGFR–Ras–Raf–MEK–ERK pathway has been attempted." (PMID 33096942, 2020). "Although various EGFR inhibitors are currently under clinical use, it is unknown how much its anti-cancer activity is attributable to SOX2 depletion." (PMID 31748974, 2020).
cancer (continued). "Several studies have reported that simultaneous inhibition of EGFR and mTOR could provide a synergistic antitumour effect in various human cancers, including TNBC20–23." (PMID 32286420, 2020). "Consequently, we have developed and utilized EGFR-targeted lipodisks for delivery of different classes of anti-cancer drugs." (PMID 32325827, 2020). "For this reason, EGFR is a major marker for cancer diagnosis." (PMID 33158043, 2020). "The following studies demonstrate how photoimmuno-chemotherapy addresses one of the major challenges facing PIT (i.e., PIC uptake) and provides compelling evidence that cooperative targeting EGFR, mitochondrial, and DNA can markedly improve treatment efficacy against cancer." (PMID 31898555, 2020). "Furthermore, monitoring genomic alterations in RAS, BRAF and other cancer-related genes in plasma can guide targeted therapeutic strategies and especially optimize anti-epidermal growth factor receptor (EGFR) therapy for metastatic CRC (mCRC)." (PMID 33066758, 2020). "Additionally, 337 hypermethylated-downregulated genes were detected and involved in pathways in cancer, focal adhesion, sphingolipid signaling pathway, EGFR tyrosine kinase inhibitor resistance, cellular senescence." (PMID 32192517, 2020). "They found that TMEM16A overexpression correlated with EGFR pathway upregulation and poor prognosis as in other cancers, and, as expected, treating cells with EGF induced the release of intracellular calcium, TMEM16A-mediated chloride current, and SOCE mediated by Orai1 and TRPC1." (PMID 32575848, 2020). "Our data supported that the downregulation of ARL4C upregulated β-catenin via activation of JAK2/STAT5, which could help the EGFR-path-blocked cancer cells to regain their malignant behaviors." (PMID 33194732, 2020). "EGFR is a verified therapeutic target; antibody drugs such as cetuximab and panitumumab, which target the transmembrane protein epidermal growth factor receptor (EGFR), have made a major step forward in the treatment of cancer." (PMID 32452127, 2020). "Thus, as one of the target genes of ERRα, GREM1 can again activate the EGFR–ERRα axis and eventually functions as an enhancer or an amplifier for the expression of genes involved in cancer cell growth and proliferation." (PMID 32572171, 2020). "Conversely to TKIs, mAbs partly exert their cytotoxic effects by reducing EGFR ectodomain density through induction of receptor mediated endocytosis or by activating antibody-dependent cellular cytotoxicity (ADCC) towards EGFR positive cancer cells." (PMID 33014289, 2020). "We also showed that the translocation of EGFR from the membrane into the cytoplasm was related to clinical activation of cancer, as correlations between EGFR cytoplasmic staining and final orbital exenteration, and between decreased EGFR membrane staining and PFS were noted." (PMID 32833992, 2020). "For cancers, EGFR overexpression and constitutive activation are related with a poor prognosis." (PMID 33037736, 2020). "The epidermal growth factor receptor (EGFR) signaling is important for normal development, such as vulval development in Caenorhabditis elegans, and hyperactivation of the EGFR is often associated with cancer development." (PMID 33092268, 2020). "In summary, incorporation of EGFR in EVs appears to have major relevance in EV-mediated immune modulation with wide ranging consequences impacting also current therapeutic approaches in cancer clinical practice." (PMID 33228060, 2020). "Indeed, some authors showed how, in combination with established therapeutic agents, AC-93253 iodide, a Src-EGFR crosstalk inhibitor, blocked cancer cell growth and motility." (PMID 32498343, 2020).
cancer (continued). "Affibody molecules binding specifically to several cancer relevant cell surface receptors have been generated, including epidermal growth factor receptor (EGFR), HER2, human epidermal growth factor receptor 3 (HER3), insulin-like growth factor 1 receptor (IGF1R), and carbonic anhydrase IX (CAIX)." (PMID 32344762, 2020). "Notably, both EGFR and c-Met play an important role in drug resistance mechanisms and both are highly overexpressed in many cancer types including PDAC." (PMID 32397114, 2020). "Additionally, some ROS1-positive cancers demonstrate a second driver mutation, mainly KRAS and EGFR, after initial treatment with a TKI." (PMID 33172113, 2020). "This might, at least partially, contribute to the uncontrolled tumor growth even under nutrition limited environments and the poor efficacy of growth factor inhibitors (e.g., EGFR inhibitors) in some refractory cancers such as NSCLC and GBM." (PMID 32411609, 2020). "In addition, serine protease inhibitor Kazal-type 6 (SPINK6) can promote cancer metastasis by binding and activating EGFR in NPC." (PMID 33093441, 2020). "Since all patients included in our study who received ALK-TKIs therapy were diagnosed as ADCs and received ALK-TKIs as all line treatments, so we further performed subgroup analysis in patients with EGFR-TKIs therapy based on pathological type of cancer, and treatment line." (PMID 32299384, 2020). "Epidermal growth factor receptor I (EGFR) is overexpressed in all aggressive cancers of epithelial origin, including squamous cell head and neck (90–100%), glioma (90–100%), non-small cell lung (75–90%), colorectal (80–85%), breast (20–30%), and cervical cancers." (PMID 33233524, 2020). "In particular, a better understanding of the regulation of EGFR glycosylation may provide novel insights into cancer biology and suggest possible therapeutic strategies, especially in the field of drugs against EGFR." (PMID 33233823, 2020). "Recent studies have also found that miR-34a can down-regulate Wnt/β-catenin signaling pathway, epidermal growth factor receptor, caspase family-associated protein and EMT in various cancer tissues and inhibit cell proliferation, promote apoptosis and inhibit metastasis." (PMID 32700738, 2020). "Also, our study showed that HD-SB induced cancer cell apoptosis via EGFR/PPARγ/PI3K/AKT pathway and lays a solid foundation for further studies of the herb pair in cancer treatment." (PMID 32265701, 2020). "In this study, the five anti-EGFR sdAbs of only 15 kDa were identified and could specifically bind to EGFR and the human cancer cells." (PMID 33023595, 2020). "Moreover, the location of the primary cancer – left versus right hemicolon – has been recognized as important prognostic and predictive factor, particularly regarding the efficacy of epidermal growth factor receptor (EGFR) antibodies." (PMID 32293337, 2020). "In addition, the results of cell cytotoxicity, apoptosis in U-87MG, SW480, and SK-Mel 28 cancer cell lines confirmed that the C225-PLGA-NPs can be utilized as a versatile nanocarrier for the management of EGFR overexpressing cancers." (PMID 33321953, 2020). "Taken together, EGFR signaling might promote cancer progression partially through activation of IRE1α-XBP1s pathway." (PMID 32489465, 2020). "The EGFR protein triggers a signaling cascade in cancer, which may be blocked by anti-EGFR drugs; however, this is only effective if KRAS, which is downstream of EGFR, is not mutated." (PMID 31990579, 2020). "Moreover, the expression of EGFR by cancer cells in HNSCC tissues was also confirmed for 25 independent patient samples." (PMID 31906300, 2020). "Co-targeting EGFR and autophagy impairs cancer cell survival in response to chemotherapy." (PMID 31896739, 2020). "Thus, following SCLC transformation, cancer cells became insensitive to EGFR-TKIs partly by downregulating the expression of EGFR protein and not by acquiring a secondary EGFR-mutation such as T790M." (PMID 35582610, 2020).